VEGFA (vascular endothelial growth factor A)
Description:
[N-VEGF]: Participates in the induction of key genes involved in the response to hypoxia and in the induction of angiogenesis such as HIF1A. Involved in protecting cells from hypoxia-mediated cell death (By similarity). [VEGFA]: Growth factor active in angiogenesis, vasculogenesis and endothelial cell growth. Induces endothelial cell proliferation, promotes cell migration, inhibits apoptosis and induces permeabilization of blood vessels. Binds to the FLT1/VEGFR1 and KDR/VEGFR2 receptors, heparan sulfate and heparin. Binds to the NRP1/neuropilin-1 receptor. Binding to NRP1 initiates a signaling pathway needed for motor neuron axon guidance and cell body migration, including for the caudal migration of facial motor neurons from rhombomere 4 to rhombomere 6 during embryonic development (By similarity). Also binds the DEAR/FBXW7-AS1 receptor. [Isoform VEGF165B]: Binds to the KDR receptor but does not activate downstream signaling pathways, does not activate angiogenesis and inhibits tumor growth.
Synonyms: L-VEGF; VPF; VEGF; VEGF-A; MVCD1
Tractability: Small molecule: a structure with a bound ligand is known; a high-quality ligand is known; it has a binding pocket of medium quality. Antibody: an approved drug acts on it; UniProt places it where antibodies can reach, with high confidence; its Gene Ontology location is reachable by antibodies, with high confidence. PROTAC: a small molecule that binds it is known. Other modalities: an approved drug acts on it.
Target class: Secreted protein
Safety:
Unwanted effects reported when the protein is acted on. In parentheses: how it was acted on, where the effect was seen, and who reports it.
Increase, Early Life Stage Mortality (inhibition; source: AOP-Wiki)
gastrointestinal toxicity (source: ClinPGx)
grade 3 hypertension (source: ClinPGx)
hand-foot syndrome (source: ClinPGx)
increase in systolic blood pressure and grade 3 hypertension (source: ClinPGx)
Gene: Protein-coding gene on chromosome 6 (43,770,184 to 43,786,487, forward strand). Ensembl gene ENSG00000112715.
Subcellular location: Cytoplasm (N-VEGF); Nucleus; Secreted (VEGFA); Endoplasmic reticulum (Isoform L-VEGF189); Golgi apparatus; Secreted, extracellular space, extracellular matrix; Secreted (Isoform VEGF121); Secreted (Isoform VEGF165); Secreted (Isoform VEGF189)
Pathways (Reactome):
Signal Transduction: Signaling by VEGF; VEGF binds to VEGFR leading to receptor dimerization; VEGF ligand-receptor interactions; VEGFA-VEGFR2 Pathway; VEGFR2 mediated cell proliferation
Cellular responses to stimuli: Regulation of gene expression by Hypoxia-inducible Factor
Disease: Potential therapeutics for SARS
Gene expression (Transcription): TFAP2 (AP-2) family regulates transcription of growth factors and their receptors
Hemostasis: Platelet degranulation
Immune System: Interleukin-4 and Interleukin-13 signaling
Gene Ontology:
Molecular function: chemoattractant activity; cytokine activity; fibronectin binding; growth factor activity; heparin binding; identical protein binding; platelet-derived growth factor receptor binding; protein binding; receptor ligand activity; transmembrane receptor protein tyrosine kinase activator activity; vascular endothelial growth factor receptor 1 binding; vascular endothelial growth factor receptor 2 binding; vascular endothelial growth factor receptor binding; extracellular matrix binding
Biological process: angiogenesis; branching involved in blood vessel morphogenesis; cell migration involved in sprouting angiogenesis; cellular response to hypoxia; cellular response to vascular endothelial growth factor stimulus; cellular stress response to acid chemical; endothelial cell chemotaxis; macrophage differentiation; monocyte differentiation; negative regulation of adherens junction organization; negative regulation of apoptotic process; negative regulation of blood-brain barrier permeability; negative regulation of cell-cell adhesion mediated by cadherin; negative regulation of establishment of endothelial barrier; negative regulation of gene expression; negative regulation of nitric oxide-cGMP mediated signal transduction; negative regulation of transcription by RNA polymerase II; phospholipase C-activating G protein-coupled receptor signaling pathway; positive chemotaxis; positive regulation of angiogenesis; positive regulation of blood vessel branching; positive regulation of blood vessel endothelial cell migration; positive regulation of blood vessel endothelial cell proliferation involved in sprouting angiogenesis; positive regulation of cell adhesion; positive regulation of cell migration; and 67 more
Cellular component: adherens junction; cell surface; cytoplasm; endoplasmic reticulum; extracellular region; Golgi apparatus; nucleus; secretory granule; VEGF-A complex; extracellular matrix; platelet alpha granule lumen; membrane
Genetic constraint (gnomAD): Loss-of-function variants: 20 observed, 47.66 expected, observed/expected ratio (o/e) 0.42, 90% interval 0.29 to 0.61. The upper end of that interval is the gene's LOEUF score, 0.61, which puts it in group 2 of 6, group 1 being the genes least tolerant of losing a copy. Missense variants: 505 observed, 517.71 expected, observed/expected ratio (o/e) 0.98, 90% interval 0.91 to 1.05. Synonymous variants: 219 observed, 206.9 expected, observed/expected ratio (o/e) 1.06, 90% interval 0.95 to 1.18.
Gene-disease validity (ClinGen):
ClinGen rates the evidence that VEGFA causes each of these diseases.
congenital heart disease (autosomal dominant): Limited. A heart disease that is present at birth.
Homologues: Orthologues: chimpanzee VEGFA (99% identical), macaque VEGFA (98% identical), pig VEGFA (93% identical), rabbit VEGFA (91% identical), dog VEGFA (84% identical), rat Vegfa (84% identical), mouse Vegfa (84% identical), guinea pig Vegfa (44% identical), tropical clawed frog vegfa (35% identical), zebrafish vegfab (29% identical), zebrafish vegfaa (28% identical). Paralogues in human: PGF (18% identical), VEGFC (15% identical), VEGFD (15% identical), VEGFB (14% identical).
Diseases named in the same sentence as VEGFA in open-access papers:
VEGFA is named in the same sentence as 1,670 diseases in open-access papers, as found by Europe PMC text mining. Sharing a sentence is not in itself a finding about the gene and the disease. The quoted sentences say what the papers report.
breast cancer (2,109 papers, 1999 to 2026). A primary or metastatic malignant neoplasm involving the breast. "The overexpression of VEGFA has been associated with poor prognosis in multiple cancers, including breast cancer, due to its role in promoting angiogenesis and enhancing the metastatic potential of tumor cells." (PMID 39684488, 2024). "HIF-1α induces VEGFA production by both breast cancer stroma and tumor-associated macrophages, which make up ~50% of the total cellular mass in breast cancers." (PMID 39439572, 2024). "This is in line with data from a murine breast cancer model demonstrating that upstream inhibition of COX2 in macrophage leads to downregulation of VEGFA, VEGFC and MMP9 associated with reduced metastasis." (PMID 36551640, 2022). "In sum, the cumulative data point to profound effects of GPx2 loss on mammary tumor progression, resulting in ROS/HIF1α/VEGFA signaling, causing vascular malfunction and hypoxia." (PMID 35193955, 2022). "miR-20a was also found to induce angiogenic effects in breast cancer cell lines, with its expression associated with increases in mean vessel size, VEGFA expression and the presence of glomeruloid microvascular proliferations." (PMID 33477629, 2021). "Hypoxia has also been found to affect the expression of the gene encoding EDN1 in U87 glioma cells and the genes encoding PTGS2 and VEGFA in breast cancer and melanoma cells." (PMID 34098948, 2021). "First, TGFβ1 and IL8 had higher average expression levels in more malignant cell lines; second, MIF and VEGFA had higher average expression levels in more malignant breast cancer tissues, and the high expression levels were associated with poor survival rate." (PMID 31293831, 2019). "This indicated that VEGFa participated in the ACE2-mediated inhibition of breast cancer angiogenesis, and the underlying mechanism was studied further." (PMID 31023337, 2019). "For example, TGFB1 and VEGFA are inferred to be the top two key genes mediating obesity-breast cancer connection in modules associated with brain development." (PMID 29156709, 2017). "Sox2 upregulation by VEGFA mediates the loss of miR-452, and miR-452 loss is required for Slug upregulation and for VEGFA-driven cell motility, invasion and metastasis in breast cancer models." (PMID 28504716, 2017). "We found that the mechanism underlying ZEB1-stimulated angiogenesis is the induction of VEGFA production by breast cancer cells." (PMID 26882471, 2016). "A study in Polish, German and Swedish breast cancer patients showed that VEGFA −2578 AA was associated with a low grade tumor." (PMID 23203097, 2012). "Polymorphisms of VEGFA alter the levels of expression and subsequently influence the susceptibility and aggressiveness of breast cancer." (PMID 23203097, 2012). "The correlation between VEGFA polymorphisms and breast cancer susceptibility and aggressiveness remains inconsistence." (PMID 23203097, 2012). "Vascular endothelial growth factor-A expression has previously been shown to be significantly associated with MVD in breast cancer." (PMID 19623180, 2009). "This hints at some indirect transcriptional control of ERO1 on VEGFA and might explain the lower levels of VEGFA mRNA in ERO1-deficient breast cancer cells." (PMID 38007054, 2024). "Thus, it is also necessary to explore the association of VEGFA gene polymorphism with the occurrence of second primary lung cancer in breast cancer patient in future relevant studies." (PMID 35668376, 2022). "As a result, it suggests that VEGFA could be a suitable diagnostic biomarker for, e.g., mammary carcinoma." (PMID 36230822, 2022). "The overexpression of VEGFA was implicated in the poor outcome of breast cancer." (PMID 33035235, 2020). "In dogs with mammary tumors, high VEGFA gene expression has been associated with poor outcome, with one study suggesting that it could be used as a prognostic marker to identify dogs at risk of disease progression." (PMID 33282935, 2020).
breast cancer (continued). "Moreover, NCOA1 is recruited to the VEGFa promoter by associating with HIF1α and c-Fos in breast cancer cells." (PMID 26287601, 2015). "Assessment of VEGFA polymorphisms may be used for evaluation of breast cancer susceptibility, aggressiveness and identification of patients that are suitable for anti-VEGFA therapy." (PMID 23203097, 2012). "An EMT program in breast cancer cells is linked to increased vascular endothelial growth factor A expression, increasing angiogenesis and the capacity for tumor initiation, a mechanism that could explain these correlated tumor and stromal phenotypes and their association with poor outcome." (PMID 39808504, 2025). "Thus, we speculate that VEGFA secreted by M2-type macrophages may be positively associated with breast cancer mobility and stemness." (PMID 38169627, 2024). "Based on above information, we speculated that FGF10 and VEGFA might play an essential role in the screening and clinical intervention for second primary lung cancer of high-risk breast cancer patients, but further investigation should be conducted to verify this conjecture." (PMID 35668376, 2022). "Studies showed that oridonin could inhibit VEGFA-associated angiogenesis of breast cancer." (PMID 35813296, 2022). "We propose that the recruitment of macrophages into obese breast tissue results in increased production of pro-angiogenic signaling, particularly VEGFA, which could promote tumor vascularization and represents a mechanism whereby obesity enhances the risk of breast cancer metastasis." (PMID 32318345, 2020). "Compared with normal breast epithelium cells, RFX5, VEGFA were upregulated in breast cancer cells, IKZF2, NAB1, S100B were downregulated in breast cancer cells while F2R, S1PR2 showed no significance." (PMID 40520263, 2025). "In vivo breast cancer models have shown that TAM-derived VEGFA can promote tumor metastasis by stimulating tumor cell intravasation and extravasation." (PMID 39941714, 2025). "Compared with normal breast epithelium cells, the expression levels of RFX5, VEGFA were significantly upregulated in breast cancer cells." (PMID 40520263, 2025). "It has been revealed that hypoxia activates the hypoxia-inducible factor 1-alpha (HIF1α)/vascular endothelial growth factor A (VEGF-A) axis in breast cancer to promote angiogenesis." (PMID 41148827, 2025). "TGFβ stimulated genes matrix metallopeptidase 2 (MMP2), epiregulin (EREG), and vascular endothelial growth factor A (VEGFA) were also critical regulators of lung metastasis of breast cancer and correlated with the prognosis of breast cancer." (PMID 38245723, 2024). "Previous research has described a downregulation of miR-185-5p in breast cancer, where the miR-185-5p expression was influenced by vascular endothelial growth factor A (VEGFA), a key molecule involved in the formation of blood vessels." (PMID 38994952, 2024). "In relation to ER, PR and HER2, we found that VEGFA expression was significantly higher in ER− and PR− breast cancer tissues compared to ER+ and PR+ tissues." (PMID 39508048, 2024). "Studies have shown that COX‐2 expression is positively correlated with CD31 and VEGFA expression in breast cancer." (PMID 39554336, 2024). "In conclusion, our work supports the evidence that interfering with VEGFA/ VEGFR2/ integrin β3 pathway can directly affect breast cancer cell migration beyond the largely explored anti-angiogenic function." (PMID 38321003, 2024). "Angiotensin-converting enzyme 2 (ACE2) inhibits breast cancer angiogenesis via suppressing the VEGFa/VEGFR2/ERK pathway." (PMID 38953895, 2024). "In this analysis, VEGFA was the most abundant pro-angiogenic gene expressed in breast cancer tissues as demonstrated by the mRNA transcript levels." (PMID 39302921, 2024).
breast cancer (continued). "Chang and colleagues found that the YTHDF3 upregulates its own protein expression through automatic regulation and then binds to m6A-enriched VEGFA mRNA to increase VEGFA expression and angiogenesis in brain metastases of breast cancer in humans." (PMID 39691597, 2024). "Apart from apoptotic death in breast cancer cells, AgNPs also cause restriction on transcription of hypoxia-inducible factor-1 (HIF-1) and induces the expression of vascular endothelial growth factor-A (VEGF)." (PMID 37668757, 2024). "The failure of exogenous hVEGF165 to stimulate the invasiveness and sphere formation of NRP-1-silencing breast cancer cells further supported the importance of NRP-1 in VEGFA-mediated signaling and function." (PMID 38169627, 2024). "For instance, ACE2 represses breast cancer cell angiogenesis via downregulating VEGFA, as well as decreasing the phosphorylation of ERK1/2, MEK1/2, and VEGFR2 in HUVEC25." (PMID 38055382, 2023). "Then Western blotting further showed that LAMP2A knockdown led to decreased protein level of VEGFA in breast cancer cells, while LAMP2A overexpression promoted the VEGFA protein level in breast cancer cells." (PMID 36913368, 2023). "In breast cancer, a subpopulation of perivascular TAMs has been identified that has high levels of the TEK receptor tyrosine kinase and expresses VEGFA, which increases vasculature leakiness and causes tumor cell intravasation." (PMID 37490147, 2023). "The literature has reported that VEGFA expression was significantly increased in breast cancer and head and neck cancer." (PMID 37852616, 2023). "In the 4T1 mammary tumour tissues harvested from hesperidin‐treated mice, we observed a significant downregulation in the VEGFa, VEGFR2, CD110 and COX2 genes." (PMID 37581480, 2023). "It is suggested that ACE2 inhibits angiogenesis by suppressing the VEGFa/VEGFR2/ERK pathway in breast cancer." (PMID 37891636, 2023). "YTHDF3 is another organ-specific metastasis driver that regulates the translation of key metastasis genes such as T6GALNAC5, GJA1, EGFR, and VEGFA to promote breast cancer brain metastasis." (PMID 38102722, 2023). "NEDD4L has been identified as an E3 ligase that mediates the ubiquitination and downregulation of PIK3CA, the catalytic subunit of class IA PI3Ks, thereby inhibiting the PI3K-AKT signaling pathway and VEGFA secretion in breast cancer." (PMID 38027016, 2023). "miR-16-5p suppresses the proliferation and invasion of breast cancer cells and promotes their apoptosis by targeting the vascular endothelial growth factor-A." (PMID 36984512, 2023). "The miR-205 has been reported to directly bind the 3’ UTR region of VEGFA mRNA to negatively control its expression in several cell types, such as breast cancer, colorectal cancer and bladder cancer as well as endothelial cells." (PMID 36158698, 2022). "VEGFA is upregulated in breast cancers overexpressing the receptor tyrosine kinase human epidermal growth factor 2 (HER2)." (PMID 36074318, 2022). "In breast cancer, angiotensin-converting enzyme 2 inhibited endothelial cells proliferation, tube formation, and migration through the phosphorylation of VEGFR2, MEK1/2, and ERK1/2 in HUVECs through the downregulation of VEGFA in breast cancer cells." (PMID 35563650, 2022). "The involvement of the PI3K-Akt pathway in the expression of VEGFA in human breast cancer cells was previously reported." (PMID 36096830, 2022). "The interaction of VEGFA and VEGF receptors (VEGFR) and the resulting angiogenesis have been heavily implicated in breast cancer development, progression, and metastasis." (PMID 36074318, 2022). "The inhibitory effect of miR-16 -5p in breast cancer cells proliferation and invasiveness can be mediated through regulation of Vascular Endothelial Growth Factor A (VEGFA) expression." (PMID 36348403, 2022). "For relapse-free survival, breast cancer patients with higher expression of VEGFA, EZH2, CASP3, WWP1, CUL2, and COL3A1 had poorer prognosis." (PMID 35812757, 2022).